MTOR (mechanistic target of rapamycin kinase)
Diseases named in the same sentence as MTOR in open-access papers (continued):
Sharing a sentence is not in itself a finding about the gene and the disease.
hepatitis B (17 papers, 2014 to 2024). "Another mTOR inhibitor, sirolimus, has also been reported to be associated with the reactivation of hepatitis B with octreiotide previously." (PMID 33868173, 2021). "Among the top 20 significant KEGG pathways, the mTOR signaling pathway was the most significant, followed by the hepatitis B and Hippo signaling pathways." (PMID 36561044, 2022). "To further elucidate the role of circRNA-100338 in the regulation of mTOR signaling pathway, we collected 122 tumor samples of hepatitis B-related HCC patients." (PMID 31157168, 2019). "In conclusion, elevated circRNA-100338 activates mTOR signaling pathway in HCC via circRNA-100338/miR-141-3p/RHEB axis and associates with poor prognosis of hepatitis B-related HCC patients." (PMID 31157168, 2019). "More importantly, activated mTOR signaling pathway by circRNA-100338/miR-141-3p/RHEB axis showed high correlation with poor prognosis in hepatitis B-related HCC." (PMID 31157168, 2019). "Integrated analysis of circRNA-100338, miR-141-3p, and target genes revealed that RHEB, a key regulator in mTOR signaling pathway, was the target of miR-141-3p in hepatitis B-related HCC." (PMID 31157168, 2019). "Our research proposed that MTOR, MAPK3, and EGFR are directly involved in hepatitis B pathways." (PMID 35745580, 2022). "In accordance with experiments in vitro, hepatitis B-related HCC tissues in circRNA-100338-high group also showed elevated expression of both RHEB, mTORC1, and EIF5, further demonstrating that circRNA-100338 could promote activation of mTOR signaling pathway." (PMID 31157168, 2019). "In accordance with HCC cell lines with overexpression of circRNA-100338, hepatitis B-related HCC tissues in circRNA-100338-high group also showed high activity of mTOR signaling pathway, further demonstrating that circRNA-100338 could promote activation of mTOR signaling pathway." (PMID 31157168, 2019).
Macrocephaly (17 papers, 2015 to 2025). Occipitofrontal (head) circumference greater than 97th centile compared to appropriate, age matched, sex-matched normal standards. "It is highly possible that the incidence of macrocephaly is determined by the enzyme activity change caused by gene mutations and the way mTOR pathway is activated." (PMID 39201832, 2024). "Finally, we note that the co-occurrence of polymicrogyria and macrocephaly should raise suspicion of gene variants that modulate the mTOR pathway." (PMID 37486637, 2023). "However, individuals with polymicrogyria and documented macrocephaly had variants only in genes encoding components of or related to the mTOR pathway (PIK3R2, PI3KCA, AKT3, and PTEN)." (PMID 37486637, 2023). "Neurodevelopmental disorders associated with hyperactive mTOR signaling, also known as mTORopathies, are caused by loss-of-function mutations in negative regulators of mTORC1, and usually manifest with symptoms that include epileptic seizures and macrocephaly." (PMID 35977929, 2022). "Among the 35 patients presenting with ID, macrocephaly, and a de novo mutation, we found a significant enrichment (p = 9.084e−09) for de novo mutations within genes of the mTOR pathway (9/14) compared to genes that operate in mTOR independent pathways (26/539)." (PMID 29051493, 2017). "Mutations in Mammalian target of rapamycin (MTOR), which is downstream of the PI3K/AKT pathway, have been identified in patients with macrocephaly." (PMID 36845425, 2023). "The MTOR pathway has been identified as important for proper synaptogenesis, suggesting a mechanistic role for abnormal synaptogenesis in the etiology of macrocephaly." (PMID 36845425, 2023). "The data are in line with the theory that the dysregulation of mTOR is central to multiple forms of developmental megalencephaly and macrocephaly." (PMID 34576223, 2021). "Investigations of PI3K/AKT/mTOR pathway should be performed in patients with severe macrocephaly and unspecific physical overgrowth." (PMID 31290289, 2019). "Finally, we propose the use of the umbrella term “mTOR pathway-related macrocephaly spectrum” to emphasise the overlapping clinical phenotypes and genotypes associated with this spectrum of patients." (PMID 29296277, 2017). "Since these patients share overlapping phenotypes and mutations in the same pathway, we propose the umbrella term “mTOR pathway-related macrocephaly spectrum” to encompass patients with macrocephaly and DD/ID/ASD associated with germline or somatic mutations in the PI3K-AKT-mTOR signalling pathway." (PMID 29296277, 2017). "Recently, mutations in other genes in the PI3K-AKT-mTOR signalling pathway, including PIK3CA, PIK3R2, MTOR, CCND2 and PPP2R5D, were also reported in patients with ASD/DD and macrocephaly." (PMID 29296277, 2017).
mucositis (17 papers, 2012 to 2025). Mucositis is inflammation and damage of the mucous membranes lining the mouth and other parts of the gastrointestinal (GI) tract. "A significant proportion (n = 14, 60.9%) of patients on mTOR inhibitors experienced adverse events, most common of which was oral mucositis or ulcer (n = 8, 34.8%), followed by infection (n = 4, 17.4%)." (PMID 35585116, 2022). "Notably, mucositis due to mTOR inhibitors administration is the main AE reported in the drug therapy cohort (88.2%)." (PMID 37029779, 2024). "Although both chemotherapy and radiotherapy can lead to the formation of oral mucositis, patients treated with mammalian target of rapamycin (mTOR) inhibitors, such as everolimus, are especially vulnerable to mucositis (73.4% of patients, with over 30% of those being severe cases)." (PMID 36902486, 2023). "However, during the development of mucositis, a reduction in mTOR activity stimulates the translation of more proinflammatory cytokines, eventually leading to a cascade of processes and the development of oral ulcers." (PMID 36902486, 2023). "Others have demonstrated that treatment with the mTOR inhibitor rapamycin prevented the increase in SA-β-gal activity in cells exposed to DNA-damaging agents and protected mice from radiation-induced mucositis in vivo." (PMID 24205274, 2013). "Similarly, dexamethasone-containing mouthwashes (0.5 mg/5 mL oral solution) are specifically recommended for prophylaxis of mTOR (mammalian target of rapamycin)-induced-mucositis in patients with metastatic breast cancer, even if a proper randomized, placebo-controlled trial is still missing." (PMID 31226812, 2019).
nonalcoholic steatohepatitis (17 papers, 2018 to 2026). "Scoparone reduced hepatic inflammation and regulated autophagy in nonalcoholic steatohepatitis mice through PI3K/AKT/mTOR pathway regulation in macrophages." (PMID 40427533, 2025). "Dr. Liu found that scoparone improves liver inflammation and autophagy by inhibiting the PI3K/AKT/mTOR pathway in mice with non-alcoholic steatohepatitis." (PMID 36277879, 2022). "mTOR acts as a regulator that controls cell metabolism, growth, and proliferation, and its inhibitor, rapamycin, has demonstrated efficacy in reducing inflammation and fibrosis, such as in non-alcoholic steatohepatitis." (PMID 40396273, 2025). "Scoparone ameliorated hepatic inflammation of mice with nonalcoholic steatohepatitis by regulating the ROS/P38/Nrf2 axis and PI3K/AKT/mTOR pathway in macrophages." (PMID 35464384, 2022). "In addition, 8-hydroxydeoxyguanosine, L-arginine, and glucose metabolites were reported to be overexpressed in T2DM and non-alcoholic steatohepatitis (NASH)-associated HCC and might participate in cell proliferation, mTOR pathways, and the activation of oxidative stress resistance." (PMID 35888734, 2022). "AA-24-a was shown to ameliorate nonalcoholic steatohepatitis by inhibiting oxidative stress and stimulating autophagy in both mouse model and human hepatic stellate cells, and to stimulate autophagy via the AMPK/mTOR/ULK1 pathway." (PMID 33888116, 2021). "A recent study indicates that scoparone could improve hepatic autophagy and inflammation in non-alcoholic steatohepatitis mice through the regulation of the ROS/p38/nuclear factor erythroid 2-related factor 2 (Nrf2) axis and PI3K/AKT/mTOR cascade in macrophages." (PMID 33390956, 2020).
overnutrition (17 papers, 2012 to 2026). An imbalanced nutritional status resulting from excessive intake of nutrients. "At least three signaling pathways are involved in SGLT2 inhibitor’s effect on autophagy flux in overnutrition diseases: mammalian target of rapamycin (mTOR), sirtuin 1 (SIRT1), and hypoxia-inducible factors (HIFs) pathways." (PMID 34744742, 2021). "Examination of these signaling pathways that indirectly regulate autophagy through mTOR in overfed fetal and neonatal hearts demonstrated that overnutrition alters signaling that regulates autophagy in offspring of obese ewes." (PMID 35173761, 2021). "In overnutrition, mTOR is activated by glucose, insulin signal, or amino acids, before forming mTOR signaling complex 1 (mTORC1), which inhibits the transcription of lysosomal enzymes and inhibits autophagosome formation." (PMID 32517059, 2020). "The activation of effector T (Teff) cells and M1 macrophages is highly dependent on the phosphatidylinositol-3 kinase (PI3K)-Akt-mechanistic target of rapamycin (mTOR) signaling, and persistent activation of this pathway by overnutrition drives M1-skewed inflammation." (PMID 33613560, 2020). "Moreover, nutrient-promoted insulin secretion and mTOR activation are temporary and reversible processes that are relieved by nutrient removal, indicating that overnutrition does not promote cancer onset through promoting mutations." (PMID 28878358, 2017). "Overnutrition affects key cellular metabolic pathways, including insulin/insulin-like growth factor signaling (IIS), the mammalian target of rapamycin (mTOR), and AMP-activated protein kinase (AMPK)." (PMID 39857433, 2025). "Overnutrition disturbs key metabolic pathways, including insulin/insulin-like growth factor signaling (IIS), the mammalian target of rapamycin (mTOR), and AMP-activated protein kinase." (PMID 39857433, 2025).
prion disease (17 papers, 2009 to 2025). A transmissible disease that is caused by a protein that is able to induce abnormal folding of normal cellular proteins, leading to characteristic spongiform brain changes, which are associated with neuronal loss without an inflammatory response. "We observed downregulation of REST, the inhibition of autophagy system-associated Akt-mTOR signaling pathway and the partially inactivation of the Wnt-β-catenin signaling pathway in the in vitro and in vivo prion disease models." (PMID 28515679, 2017). "Metabolic dysfunction pathways (e.g., mTOR signaling) and prion disease pathways are also consistent with known mechanisms in ALS participants." (PMID 34776863, 2021). "Analysis with DIANA-miRpath (v.3.0) showed that combinations of at least two miRNAs overlapped in pathways such as steroid biosynthesis, proteoglycan in cancers, mTOR signaling and prion disease pathway." (PMID 32531989, 2020). "This shows the importance of small molecules for the possible treatment of patients with prion diseases by targeting mTOR-dependent and mTOR-independent pathways simultaneously." (PMID 29867448, 2018). "In conclusion, REST plays a critical neuroprotective role partly via restoring the Akt-mTOR and Wnt-β-catenin signaling pathways in prion diseases." (PMID 28515679, 2017). "We further investigated the role of REST in the Akt-mTOR and Wnt-β-catenin pathways in our in vitro prion disease model." (PMID 28515679, 2017). "A previous study demonstrated activation of the macroautophagic system in scrapie-infected experimental rodents and in certain human prion diseases, in which the essential negative regulator mTOR is severely inhibited." (PMID 26423766, 2015). "In prion diseases, a significant reduction in PrPSc aggregates has been attained by mammalian Target of rapamycin (mTOR) dependent or independent induction of autophagy by using small molecules, like imatinib mesylate, lithium, rapamycin, trehalose, and sirtuin." (PMID 32977678, 2020). "It suggests that there might be the possibility that mTOR-dependent and mTOR-independent small molecules could be used as a combinatory treatment in patients with prion diseases." (PMID 30337853, 2018). "We postulated that the Akt-mTOR signaling pathway might be involved in REST suppression in prion diseases." (PMID 28515679, 2017). "Therefore, we further asked what the role of REST in the Akt-mTOR pathway is in prion diseases." (PMID 28515679, 2017). "In addition, mTOR is also critically involved in the regulation of autophagy, which functions in order to avoid the accumulation of aberrantly folded toxic protein aggregates, or organelles, that may contribute to protein misfolding conditions, including prion diseases." (PMID 32108870, 2020). "Here we further showed that Akt-mTOR signaling, the most important negative pathway for autophagy in mammalian cells is inhibited in prion diseases models in vitro and in vivo." (PMID 28515679, 2017). "However only 4 pathways (ubiquitin mediated proteolysis and prion disease, matches ≥ 60 bp; ALS and mTOR signaling pathway, matches of 50-59 bp) showed at least five times the expected number of genes in the infected lung." (PMID 19948073, 2009). "Furthermore, the pathways linked to GX0101-induced tumors in both the 30 dpi and 45 dpi experimental groups included mTOR, MAPK, cAMP, ECM-receptor interaction, Chemokine, JAK-STAT, MicroRNAs in cancer, ErbB, pathways in cancer, Rap1, VEGF, Ras, Wnt, Prion diseases, and Hippo pathway." (PMID 38183097, 2024). "These pathways included the Toll-like receptor, mTOR, AMPK, FoxO, B cell receptor, Jak-STAT, cAMP, Apoptosis, T cell receptor, TNF, Chemokine, PPAR, MAPK, Notch, PI3K-Akt, ErbB, Rap1, cGMP-PKG, VEGF, Calcium, Wnt, NF-κB, Ras, Hippo, Prion diseases, and Fc epsilon RI signaling pathway." (PMID 38183097, 2024).
prion disease (continued). "Other previous studies have only analyzed a limited number of protein kinases (c-Abl, Src, Fyn, Yes, Lck, Lyn, Syk, Akt, mTOR, p70S6K, CaMK2α, CDK5, PYK2, PKA, PKC, PKR, PERK, MEK1/2 and MAPKs), based mostly on their hypothesized involvement in prion disease pathogenesis." (PMID 25280966, 2014). "Thus, the pharmacological inhibition of mTOR could find rational use also in the treatment of non-inherited forms of prion disease." (PMID 36148145, 2022).
type 1 diabetes (17 papers, 2015 to 2026). "The cPKCγ knock-out could alleviate the cognitive dysfunction caused by type 1 diabetes through AMPK/mTOR mediated autophagy pathway." (PMID 36817124, 2023). "Under fasting conditions PKA and mTOR activity in human pancreatic islets with type 1 diabetes decreases, stimulating the expression of specific genes and subsequent insulin production." (PMID 40137116, 2025). "The author also performed a study on a small sample of human subjects and on human pancreatic β-cells, which highlight that the inhibition of mTOR, along with PKA, promotes Ngn3-driven β-cell regeneration in human type 1 diabetes islets." (PMID 40137116, 2025). "In human pancreatic islets with type 1 diabetes, fasting conditions decrease PKA and mTOR activity, leading to the expression of specific genes and subsequent insulin production." (PMID 38321992, 2024).
allergic asthma (16 papers, 2013 to 2025). A asthma with a basis in a pathological type I hypersensitivity reaction. "Based on these observations, we have investigated whether mTOR is associated with HIF-1α-mediated VEGF expression in allergic asthma." (PMID 24312355, 2013). "Luteolin exhibited inhibitory effects on airway inflammation in mice with allergic or neutrophilic asthma, and it modulated the PI3K/AKT/mammalian target of rapamycin (mTOR) signaling pathway to inhibit autophagy in allergic asthma." (PMID 38590639, 2024). "Luteolin inhibits autophagy in allergic asthma by activating PI3K/Akt/mTOR signaling and inhibiting the Beclin-1-PI3KC3 complex." (PMID 37513887, 2023). "The PI3K/Akt/mTOR pathway in innate immune cells inhibits autophagy in allergic asthma, and it is considered an emerging therapeutic target." (PMID 36496564, 2022). "A recent study showed the role of the mTOR signaling pathway in the pathogenesis of allergic asthma proving that upon mTOR inactivation, CD11b+ DCs of the lung can skew allergic inflammation from eosinophilic Th2 to neutrophilic Th17 polarity." (PMID 34394086, 2021). "Mouse model-based studies of targeting serine/threonine kinase mammalian target of rapamycin (mTOR) have provided several key insights into the role of mTOR-dependent signaling pathway in the pathogenesis of allergic asthma." (PMID 29387732, 2017). "Previously, our lab demonstrated that inhibition of mTOR with rapamycin prevented allergic asthma in a mouse model induced by exposure to the allergen, house dust mite (HDM)." (PMID 23349887, 2013). "In protocol two, to address the role of mTOR in chronic/established allergic asthma, mice were exposed to HDM for 6 weeks and treated with rapamycin or dexamethasone from weeks 4 to 6 of the exposure period." (PMID 23349887, 2013). "Our lab previously demonstrated that inhibition of mTOR with rapamycin prevented house dust mite (HDM)-induced allergic asthma in mice." (PMID 23349887, 2013). "We conclude that while mTOR signaling is critical during the early phases of allergic asthma, its role is much more limited once disease is established." (PMID 23349887, 2013). "Moreover, a study found that the PI3K/Akt/mTOR signal transduction pathway constitutes the intersection of allergic asthma and cataracts." (PMID 36496564, 2022). "In this study, we showed that silencing DEK significantly attenuated the activation of the PI3K/AKT/mTOR pathway, indicating that DTA‐64 could reduce the development of allergic asthma through the PI3K/AKT/mTOR pathway." (PMID 33124760, 2020). "A recent study using mice with myeloid-specific deletion of TSC1 found that TSC1-deficient mice are highly resistant to M2-polarized allergic asthma, and identified a key role for TSC1 in orchestrating macrophage polarization via mTOR-dependent and independent pathways." (PMID 28225024, 2017). "In recent years, studies showed that inhibition of mTOR could attenuate key characteristics of allergic asthma, including airway inflammation, AHR, and goblet cell metaplasia." (PMID 29234390, 2017). "In summary, we demonstrated that Rheb1-KO directly suppresses M1 and promotes M2 polarization of macrophages in an mTOR-dependent manner, and showed that its essential role in M2 activation, as well as in regulating allergic asthma, is mainly mediated by inhibiting the mTOR pathway." (PMID 28225024, 2017). "The goal of this study was to determine whether inhibition of mTOR with rapamycin would attenuate key characteristics of allergic asthma in two models that addressed chronic/established disease, namely allergen re-exposure and disease progression." (PMID 23349887, 2013). "Although this study showed that mTOR inhibition could suppress allergic asthma early in the disease process, the role of mTOR during allergen re-exposure and chronic, established allergic disease remained unclear." (PMID 23349887, 2013).